TMEM59L (transmembrane protein 59 like)
Description:
Modulates the O-glycosylation and complex N-glycosylation steps occurring during the Golgi maturation of APP. Inhibits APP transport to the cell surface and further shedding.
Synonyms: BSMAP; C19orf4
Tractability: Antibody: UniProt predicts a signal peptide or a membrane-spanning region. PROTAC: ubiquitination databases record sites on it.
Gene: Protein-coding gene on chromosome 19 (18,607,430 to 18,621,040, forward strand). Ensembl gene ENSG00000105696.
Subcellular location: Golgi apparatus membrane
Gene Ontology:
Molecular function: protein binding
Biological process: branching involved in ureteric bud morphogenesis
Cellular component: membrane; Golgi membrane
Genetic constraint (gnomAD): Loss-of-function variants: 33 observed, 37.89 expected, observed/expected ratio (o/e) 0.87, 90% interval 0.66 to 1.16. The upper end of that interval is the gene's LOEUF score, 1.16, which puts it in group 5 of 6, group 1 being the genes least tolerant of losing a copy. Missense variants: 441 observed, 417.17 expected, observed/expected ratio (o/e) 1.06, 90% interval 0.98 to 1.14. Synonymous variants: 219 observed, 180.56 expected, observed/expected ratio (o/e) 1.21, 90% interval 1.09 to 1.36.
Homologues: Orthologues: chimpanzee TMEM59L (99% identical), macaque TMEM59L (91% identical), pig TMEM59L (89% identical), guinea pig TMEM59L (85% identical), dog TMEM59L (76% identical), mouse Tmem59l (73% identical), rat Tmem59l (72% identical), zebrafish tmem59l (44% identical), tropical clawed frog tmem59l (42% identical). Paralogues in human: TMEM59 (31% identical).
Diseases named in the same sentence as TMEM59L in open-access papers:
TMEM59L is named in the same sentence as 12 diseases in open-access papers, as found by Europe PMC text mining. Sharing a sentence is not in itself a finding about the gene and the disease. The quoted sentences say what the papers report.
colorectal cancer (2 papers, 2025 to 2026). A primary or metastatic malignant neoplasm that affects the colon or rectum. "Knockdown of TMEM59L in colorectal cancer cells inhibited the migration and invasion abilities of both LoVo and HCT116 cells." (PMID 41378300, 2025). "This study aimed to investigate the role of TMEM59L in colorectal cancer (CRC) and its interaction with the TGF-β/Smad signaling pathway." (PMID 41378300, 2025). "Our study is the first to reveal the role of TMEM59L in colorectal cancer metastasis through animal and cell experiments." (PMID 41378300, 2025). "Interestingly, our data indicate that TMEM59L is expressed at lower levels in primary colorectal cancer tissues compared to adjacent normal tissues, but shows a marked increase in metastatic lesions." (PMID 41543046, 2026). "This study aimed to investigate the role of TMEM59L in regulating PTPRN‐mediated DNA damage repair and its impact on 5‐FU sensitivity in colorectal cancer, with the goal of identifying potential therapeutic targets to overcome chemoresistance." (PMID 41543046, 2026).
Anxiety (1 paper, 2025). Intense feelings of nervousness, tension, or panic often arise in response to interpersonal stresses. "Knockdown of TMEM59L reduces anxiety and depression in mice." (PMID 41378300, 2025).
glioblastoma (1 paper, 2026). The most malignant astrocytic tumor (WHO grade IV). "In glioblastoma (GBM), TMEM59L is highly expressed in recurrent tumors but low in normal brain tissue." (PMID 41543046, 2026).
glioma (1 paper, 2026). A benign or malignant brain and spinal cord tumor that arises from glial cells (astrocytes, oligodendrocytes, ependymal cells). "Radiation has been shown to induce TMEM59L expression in GBM cells, and interestingly, high TMEM59L levels are associated with better prognosis in IDH‐mutant and MGMT‐methylated gliomas, suggesting a possible connection with DNA damage repair and oxidative stress." (PMID 41543046, 2026).
lymph node metastasis (1 paper, 2023). "A uni-factor COX analysis was performed on the characteristic genes of lymph node metastasis, and three survival-related genes (p < 0.05) were obtained, including TMEM59L, CLCA1, and TUBB2B." (PMID 37719786, 2023). "Three survival-related genes (TMEM59L, CLCA1, and TUBB2B) were associated with the lymph node metastasis and survival time of patients." (PMID 37719786, 2023). "In this study, nine lymph node metastasis genes were analyzed via uni-factor COX regression, and three survival-related genes (TMEM59L, CLCA1, and TUBB2B) were ultimately identified." (PMID 37719786, 2023). "CLCA1 protein expression was lower in the lymph node metastasis group, while the TMEM59L and TUBB2B were higher in the lymph node metastasis group." (PMID 37719786, 2023). "In light of these observations and analysis in TCGA data, we hypothesized that TMEM59L, CLCA1, and TUBB2B may be the disease markers for lymph node metastasis of CRC." (PMID 37719786, 2023).
metastatic tumors (1 paper, 2026). "However, TMEM59L expression was markedly elevated in metastatic tumors compared to both primary tumors and normal tissues." (PMID 41543046, 2026).
osteoarthritis (1 paper, 2022). A noninflammatory degenerative joint disease occurring chiefly in older persons, characterized by degeneration of the articular cartilage, hypertrophy of bone at the margins and changes in the synovial membrane. "TMEM59L encodes a neuron-specific transmembrane protein mediating oxidative stress-induced cell death through caspase-3 in mice, a mechanism also associated with chondrocyte cell death in osteoarthritis experimental models." (PMID 35088088, 2022).
cancer (5 papers, 2021 to 2026). A tumor composed of atypical neoplastic, often pleomorphic cells that invade other tissues. "TMEM59L expression has been significantly correlated with immunophenoscore, neoantigen load, loss of heterozygosity, cancer stemness, and homologous recombination deficiency across various malignancies." (PMID 41543046, 2026). "Transmembrane protein TMEM59L is implicated in cancer progression, but its role in CRC chemoresistance is unclear." (PMID 41543046, 2026). "Since then, numerous studies have found that TMEM59L is associated with the survival of patients with cancers." (PMID 41378300, 2025). "This study is the first to investigate the association between TMEM59L and cancers through cell and animal experiments." (PMID 41378300, 2025). "Since TMEM59L expression was closely associated with the genomic heterogeneity of various cancers, we then performed the drug sensitivity analysis on the GDSC and CTRP databases." (PMID 36618425, 2022). "Then, mechanistic investigation is required to confirm the functional association between TMEM59L and cancer- and immune pathways, as well as the epigenetic regulation of TMEM59L expression in specific cancers." (PMID 36618425, 2022). "The results indicated that TMEM59L expression was altered in different types of cancer and associated with the clinical outcome of cancer patients." (PMID 36618425, 2022). "In conclusion, by combining a multi-omics approach, we comprehensively explored TMEM59L gene expression signature, its prognostic value, as well as its association with immune cell infiltration and cancer-associated pathways in various cancer types." (PMID 36618425, 2022). "Pathway analysis indicated that TMEM59L exerted a key influence in cancer development and in immune- and cancer-associated pathways such as epithelial–mesenchymal transition and TGF-β signaling." (PMID 36618425, 2022). "A significant correlation was also observed between TMEM59L expression and immunophenoscore, homologous recombination deficiency, loss of heterozygosity, tumor stemness score, and neoantigens in various cancers." (PMID 36618425, 2022). "In this study, we comprehensively explored TMEM59L gene expression signature, its prognostic value, as well as its association with immune cell infiltration and cancer-associated pathways in various cancer types." (PMID 36618425, 2022). "Data analysis prompted TMEM59L exerting a key influence in cancer development may associated TGF-β signaling." (PMID 41378300, 2025). "In our study, results demonstrated that overexpression of PTPRN attenuated the effect of TMEM59L silence on ROS combined with DNA damage, cell proliferation, apoptosis, metastasis, and cancer stem cells marker in CRC cells and mice bearing CRC tumor." (PMID 41543046, 2026). "Kaplan-Meier analysis revealed that patients with high TMEM59L expression had worse survival compared to those with low expression, supporting its role in cancer progression." (PMID 41378300, 2025). "To evaluate the influence of TMEM59L knocked down on cancer cell motility in vivo, we injected TMEM59L_KD cells into caudal vein of nude mice and fluorescence was observed continuously for 4 weeks, and fluorescence photographs were taken once a week." (PMID 41378300, 2025). "We further analyzed TMEM59L mRNA expression tendency at different clinical stages and in different cancer subtypes." (PMID 36618425, 2022). "Similar results were seen when assessing the correlation between RNA stemness score and TMEM59L expression in most cancers, except for GBM, GBMLGG, LGG, and PCPG." (PMID 36618425, 2022). "Considering the small number of normal samples in TCGA database, we integrated the data of normal tissues from the GTEx database with the data of TCGA tumor tissues to determine the expression characteristics of TMEM59L across the pan-cancer cohort." (PMID 36618425, 2022).
cancer (continued). "In the present research, we assessed the pan-cancer expression of TMEM59L and the correlation of dysregulation of TMEM59L expression with clinical outcome of patients." (PMID 36618425, 2022). "We also demonstrated that TMEM59L expression was negatively linked with the expression of many immune modulators, including PD-L1, IDO1, TIGIT, CTLA-4, and BTLA in various cancers." (PMID 36618425, 2022). "Our study found that in addition to regulating pathways involved in cancer progression, TMEM59L was also involved in immune regulatory pathways such as IL6-JAK-STAT3, IL2-STAT5, and TGF-β signaling." (PMID 36618425, 2022). "The results were similar; compared with its expression in normal samples, TMEM59L was significantly downregulated in most cancer types." (PMID 36618425, 2022). "This study was designed to reveal the prognostic value and the functional role of TMEM59L in cancer." (PMID 36618425, 2022). "TMEM59L expression was evidently downregulated across most cancer types compared to its expression in the corresponding normal tissues." (PMID 36618425, 2022). "We then further assessed Spearman’s correlation coefficient of TMEM59L and immune scores across distinct cancer types using the ESTIMATE algorithm." (PMID 36618425, 2022). "Compared with corresponding normal tissues, TMEM59L mRNA expression was significantly increased in six human cancers, specifically BRCA, CHOL, LIHC, LUAD, PRAD, and THCA." (PMID 36618425, 2022). "To better understand the relevance and potential functions of TMEM59L in cancer pathogenesis, we performed functional enrichment analysis on the low and high TMEM59L expression groups across several cancer types." (PMID 36618425, 2022). "Our study revealed the prognostic value as well as the genomic and immunological characteristics of TMEM59L in cancers, highlighting the promising potential for TMEM59L as a prognostic cancer biomarker and a therapeutic target." (PMID 36618425, 2022). "The role of TMEM59L is different in several types of cancers such as GBM and COAD." (PMID 41543046, 2026). "TMEM59L is a transmembrane protein belonging to the membrane transport protein family, members of which are increasingly recognized as key regulators of chemoresistance in multiple cancers." (PMID 41543046, 2026). "In 2022, the link between TMEM59L and cancers was first discovered." (PMID 41378300, 2025). "The relationship between TMEM59L and cancers was first reported in 2022." (PMID 41378300, 2025). "Interestingly, we further found that TMEM59L is negatively correlated with cancer immunity cycle pathways which further confirmed that TMEM59L is related to the immunosuppressive microenvironment." (PMID 36618425, 2022). "However, there is currently a dearth of systematic studies in the literature on the TMEM59L regulation of tumor pathophysiology across cancer types." (PMID 36618425, 2022). "Epigenetic changes such as DNA methylation play key roles in modulating the behaviors of cancer cells and immune tolerance, thus we explored whether epigenetic regulation is involved in TMEM59L mRNA expression." (PMID 36618425, 2022). "The methylation levels of TMEM59L gene in distinct cancers were highly heterogeneous." (PMID 36618425, 2022). "Moreover, the pathway activity analysis suggested that TMEM59L was significantly involved in 10 salient cancer-related pathways, namely DNA damage response, apoptosis, RTK, cell cycle, Hormone AR, Hormone ER, TSC–mTOR, Ras/MAPK, EMT and PI3K/AKT signaling pathways." (PMID 36618425, 2022). "TMEM59L is a newly discovered transmembrane protein; its functions in cancer remain unknown." (PMID 36618425, 2022). "In our study, the abnormal hypermethylation of TMEM59L was associated with decreased mRNA levels and better clinical outcomes for several cancers, such as KIRP, KIRC, and COAD, suggesting that hypermethylation of TMEM59L gene may be key regulatory mechanism for TMEM59L expression in these cancers." (PMID 36618425, 2022).
cancer (continued). "The “Target” run with ANGPTL3 as a target gene shows that altered genes of various cancer types including MAPK1, CASP5, COL3A1, ITGAM and TMEM59L change the expression of ANGPTL3." (PMID 37375208, 2023). "For this reason, we investigated the link between TMEM59L expression and the IPS across various cancer types." (PMID 36618425, 2022). "Therefore, in these specific cancer types TMEM59L may serve as a tumor promoting factor." (PMID 36618425, 2022). "Further analysis demonstrated that distinct differences was observed in different clinical stages of several cancer types, such as KIRP, BLCA, COAD, and KIRC, where advanced tumor stage correlated with higher TMEM59L mRNA expression." (PMID 36618425, 2022). "Future research directions should include detailed mechanistic studies to elucidate how TMEM59L regulates TGF-β signaling, investigation of TMEM59L function in additional cancer models, and exploration of the molecular basis for cellular heterogeneity in pathway responses." (PMID 41378300, 2025). "A significantly positive correlation between TMEM59L and stromal scores was detected, yet a negative correlation with immune scores across many cancer types." (PMID 36618425, 2022). "However, there is currently a lack of in-depth reports on the functional mechanism of TMEM59L, especially in the context of cancer research." (PMID 36618425, 2022). "Moreover, correlation analysis hinted at a negative correlation of TMEM59L expression with CD8 T cells, activated CD4 T cells, and several immunomodulators, including IDO1, TIGIT, PD-L1, CTLA-4, and BTLA in various cancers." (PMID 36618425, 2022). "Although the other five genes RPL32, TMEM59L, LOC642929, LHX2, and TLCD3B have not been identified in clinical studies indicating their effect on cancers, they may be considered candidate oncogenes because of their high ranking in our constructed gene network modules." (PMID 33708239, 2021).
tumor (5 papers, 2022 to 2026). "In the present study, we conducted correlation analyses to identify the association between TMEM59L expression and tumor stemness scores (RNA and DNA stemness scores)." (PMID 36618425, 2022). "Bioinformatics analysis revealed an unexpected pattern of TMEM59L expression: it was higher in normal colorectal tissues than in tumor tissues." (PMID 41543046, 2026). "Silencing of TMEM59L expression enhanced the inhibitory effect of 5‐FU on tumor growth in mice with CRC, while overexpression of PTPRN reversed the impact of TMEM59L silencing on tumor growth." (PMID 41543046, 2026). "A xenograft model in nude mice validated the TMEM59L/PTPRN axis on tumor growth, stemness, and EMT markers." (PMID 41543046, 2026). "This study aims to explore the effects of TMEM59L on CRC tumor cells and its relationship with the TGF-β signaling pathway through cell and animal experiments." (PMID 41378300, 2025). "Our findings revealed that TMEM59L expression was correlated with poor prognosis across multiple tumor types, especially in COAD, KIRP, and KIRC." (PMID 36618425, 2022). "This seemingly contradictory expression pattern may reflect the dynamic regulatory role of TMEM59L during tumor progression." (PMID 41543046, 2026). "Future investigations should focus on identifying the upstream regulators of TMEM59L in CRC, particularly in metastatic versus primary lesions, and clarify how these regulatory networks converge on TMEM59L to modulate its function across different tumor stages—a limitation acknowledged in this work." (PMID 41543046, 2026). "GSEA further confirmed enrichment of the TGF-β pathway in the high TMEM59L group, suggesting that TMEM59L may influence tumor biology and contribute to CRC metastasis via this pathway." (PMID 41378300, 2025). "TMEM59L remained significant after adjusting for age and gender but lost significance after stage adjustment (HR = 1.145, p = 0.457), suggesting the prognostic effect may be mediated by tumor stage." (PMID 41378300, 2025). "However, we did observe an increase in cell viability in HCT116 cells 96 hours after treatment with si-TMEM59L#3, suggesting that TMEM59L may play a role in suppressing tumor cell viability." (PMID 41378300, 2025). "This implied that the dysregulation of TMEM59L could lead to anti-tumor drug resistance." (PMID 36618425, 2022). "In summary, our study uncovers a dual role for TMEM59L in CRC: while downregulated in primary tumors, it is reactivated in metastases to drive chemoresistance—a phenomenon potentially regulated by tumor microenvironmental cues." (PMID 41543046, 2026). "Like TMEM59L, PTPRN was downregulated in tumor tissues compared to normal tissues, yet high PTPRN expression was associated with poor survival in CRC patients." (PMID 41543046, 2026).
TMEM59L also shares sentences with these, for which no sentence is quoted: bladder urothelial carcinoma (1 paper); colon adenocarcinoma (1); depression (1).